JAK1 (Janus kinase 1)
Description:
Non-membrane spanning protein tyrosine kinase that phosphorylates signal-transducing subunits of cytokine receptor complexes like IL2RB, IL10RA, IFNAR2, IL6ST, LIFR, OSMR and IL31RA. Functionnally, is involved in the IFN-alpha/beta/gamma signal pathway. Mechanistically, in response to interferon-binding to IFNAR1-IFNAR2 heterodimer, phosphorylates and activates its binding partner IFNAR2, creating docking sites for STAT proteins. Directly phosphorylates STAT proteins but also activates STAT signaling through the transactivation of other JAK kinases associated with signaling receptors. Involved in the MT-RNR2/humanin-mediated signaling pathway leading to STAT3 phosphorylation. Binding of CNTF or the CLCF1/CLF heterodimer to CNTFR leads to IL6ST/gp130-LIFR dimerization followed by activation of JAK1 and JAK2 which in turns phosphorylate IL6ST/gp130 and LIFR. The tyrosine phosphorylated signaling receptors serve in turn as docking proteins for STAT3. Involved in the oncostatin-M-mediated signaling pathway through both type I OSM receptor complex (heterodimers composed of LIFR and IL6ST) and type II OSM receptor complex (heterodimers composed of OSMR and IL6ST). Involved in the oncostatin-M-mediated signaling pathway through both type I OSM receptor complex (heterodimers composed of LIFR and IL6ST) and type II OSM receptor complex (heterodimers composed of OSMR and IL6ST). Involved in the Interleukin-31-mediated signaling pathway through the IL31 receptor complex (heterodimers composed of OSMR and IL31RA).
Synonyms: JAK1A; JAK1B; JTK3; AIIDE
Tractability: Small molecule: an approved drug acts on it; a structure with a bound ligand is known; a high-quality ligand is known; it belongs to a druggable protein family. Antibody: its Gene Ontology location is reachable by antibodies, with high confidence; UniProt places it where antibodies can reach, with medium confidence. PROTAC: it is named in the literature on targeted protein degradation; UniProt records ubiquitination sites on it; ubiquitination databases record sites on it; its protein half-life has been measured; a small molecule that binds it is known.
Target class: TK protein kinase group; Enzyme; Kinase; Protein Kinase; Tyrosine protein kinase JakA family
Chemical probes: BARICITINIB, FILGOTINIB (high quality), PD134442, PF-06263276, RUXOLITINIB (high quality), tofacitinib (high quality)
Gene: Protein-coding gene on chromosome 1 (64,833,223 to 65,067,754, reverse strand). Ensembl gene ENSG00000162434.
Subcellular location: Endomembrane system
Pathways (Reactome):
Immune System: IFNG signaling activates MAPKs; IL-6-type cytokine receptor ligand interactions; ISG15 antiviral mechanism; Inactivation of CSF3 (G-CSF) signaling; Interferon alpha/beta signaling; Interferon gamma signaling; Interleukin receptor SHC signaling; Interleukin-10 signaling; Interleukin-12 signaling; Interleukin-15 signaling; Interleukin-2 signaling; Interleukin-20 family signaling; Interleukin-21 signaling; Interleukin-27 signaling; Interleukin-35 Signalling; Interleukin-4 and Interleukin-13 signaling; Interleukin-6 signaling; Interleukin-7 signaling; Interleukin-9 signaling; Other interleukin signaling; PD-L1(CD274) glycosylation and translocation to plasma membrane; Regulation of IFNA/IFNB signaling; Regulation of IFNG signaling; Signaling by CSF3 (G-CSF)
Disease: Evasion by RSV of host interferon responses; Potential therapeutics for SARS; SARS-CoV-2 activates/modulates innate and adaptive immune responses
Signal Transduction: MAPK1 (ERK2) activation; MAPK3 (ERK1) activation; RAF/MAP kinase cascade
Cell-Cell communication: Activation of STAT3 by cadherin engagement
Gene Ontology:
Molecular function: non-membrane spanning protein tyrosine kinase activity; protein binding; protein phosphatase binding; protein tyrosine kinase activity; ubiquitin protein ligase binding; growth hormone receptor binding; ATP binding; CCR5 chemokine receptor binding; protein kinase activity
Biological process: cell surface receptor signaling pathway via JAK-STAT; ciliary neurotrophic factor-mediated signaling pathway; cytokine-mediated signaling pathway; interleukin-10-mediated signaling pathway; interleukin-11-mediated signaling pathway; interleukin-13-mediated signaling pathway; interleukin-15-mediated signaling pathway; interleukin-19-mediated signaling pathway; interleukin-2-mediated signaling pathway; interleukin-4-mediated signaling pathway; interleukin-6-mediated signaling pathway; interleukin-9-mediated signaling pathway; leukemia inhibitory factor signaling pathway; oncostatin-M-mediated signaling pathway; positive regulation of homotypic cell-cell adhesion; positive regulation of protein localization to nucleus; positive regulation of sprouting angiogenesis; protein localization to cell-cell junction; protein phosphorylation; response to antibiotic; type I interferon-mediated signaling pathway; type II interferon-mediated signaling pathway; adherens junction organization; cell differentiation; growth hormone receptor signaling pathway via JAK-STAT; and 5 more
Cellular component: cytoplasm; cytoplasmic side of plasma membrane; extrinsic component of cytoplasmic side of plasma membrane; focal adhesion; nucleus; cytosol; endoplasmic reticulum lumen; endosome; interleukin-5 receptor complex; plasma membrane; endomembrane system; membrane
Genetic constraint (gnomAD): Loss-of-function variants: 13 observed, 122.79 expected, observed/expected ratio (o/e) 0.11, 90% interval 0.068 to 0.17. The upper end of that interval is the gene's LOEUF score, 0.17, which puts it in group 1 of 6, group 1 being the genes least tolerant of losing a copy. Missense variants: 779 observed, 1,374.9 expected, observed/expected ratio (o/e) 0.57, 90% interval 0.53 to 0.6. Synonymous variants: 460 observed, 497.68 expected, observed/expected ratio (o/e) 0.92, 90% interval 0.86 to 1.
Gene-disease validity (ClinGen):
ClinGen rates the evidence that JAK1 causes each of these diseases.
autoinflammation, immune dysregulation, and eosinophilia (autosomal dominant): Definitive.
Cancer hallmarks: proliferative signalling (promotes); escaping immune response to cancer (suppresses); escaping programmed cell death (suppresses)
Homologues: Orthologues: chimpanzee JAK1 (99% identical), macaque JAK1 (99% identical), pig JAK1 (97% identical), rabbit JAK1 (96% identical), dog JAK1 (96% identical), guinea pig JAK1 (95% identical), mouse Jak1 (95% identical), rat Jak1 (95% identical), tropical clawed frog jak1 (77% identical), zebrafish jak1 (63% identical). Paralogues in human: TYK2 (46% identical), JAK2 (42% identical), JAK3 (38% identical), FRK (15% identical), PTK2 (14% identical), LYN (14% identical), FGR (14% identical), HCK (14% identical), LCK (14% identical), SRC (14% identical), YES1 (14% identical), ABL1 (13% identical), and 20 more.
Diseases named in the same sentence as JAK1 in open-access papers:
JAK1 is named in the same sentence as 442 diseases in open-access papers, as found by Europe PMC text mining. Sharing a sentence is not in itself a finding about the gene and the disease. The quoted sentences say what the papers report.
rheumatoid arthritis (160 papers, 2014 to 2026). A chronic, systemic autoimmune disorder characterized by inflammation in the synovial membranes and articular surfaces. "Small-molecule JAK1 inhibitors such as tofacitinib and baricitinib have been approved for rheumatoid arthritis but lack specificity and pose an increased risk of viral respiratory tract infection." (PMID 40733185, 2025). "Altered JAK1 signalling has been associated with T1DM previously, in studies that show JAK1 inhibition successfully ameliorated autoimmune diabetes in mice and reduced insulin dependency in a patient with rheumatoid arthritis, systemic sclerosis, and T1DM." (PMID 34769307, 2021). "Recent studies have shown that highly selective JAK1 inhibitors (such as upadacitinib and filgotinib), with lower risk of causing adverse effects, are also effective in treating rheumatoid arthritis." (PMID 34745118, 2021). "One of the new drugs that are in clinical development for IBD, but already approved for the treatment of rheumatoid arthritis, is Baricitinib, a selective Janus kinase (JAK1, JAK2) and AP2-associated protein kinase 1 (AAK1) inhibitor." (PMID 32714386, 2020). "JAK1 also has associated small molecule inhibitors which are tyrosine-protein kinase JAK1 inhibitors including abrocitinib, baricitinib and ruxolitinib, but have been primarily used in trials to treat autoimmune diseases such as atopic eczema, myelofibrosis and rheumatoid arthritis." (PMID 39565278, 2025). "The aberrant activity of JAK1 is linked with the pathogenesis of inflammatory disorders and immune diseases like rheumatoid arthritis (RA), ulcerative colitis, and Crohn’s disease." (PMID 34845259, 2021). "Baricitinib, a selective JAK1/2 inhibitor effective in inflammatory disorders such as rheumatoid arthritis, suppresses cytokine signaling, but its role in age-related osteoporosis remains insufficiently defined." (PMID 42278571, 2026). "Baricitinib, a selective oral JAK1/2 inhibitor approved for rheumatoid arthritis, has been extensively studied in SLE." (PMID 41194923, 2025). "Other small-molecule JAK1 inhibitors, such as fligotinib and upadacitinib, are in phase 3 clinical trials for rheumatoid arthritis and inflammatory bowel disease." (PMID 40733185, 2025). "Upadacitinib is an oral JAK1 inhibitor that has been found to have significant therapeutic effects in the treatment of rheumatoid arthritis, moderate to severe atopic dermatitis, and ankylosing spondylitis." (PMID 40292287, 2025). "Filgotinib, an agent that selectively inhibits JAK1, is presently being studied in clinical trials for various ailments such as rheumatoid arthritis and inflammatory bowel disease." (PMID 40162549, 2025). "Filgotinib (FIL), a Janus kinase-1 preferential inhibitor, has been studied for its efficacy and safety in rheumatoid arthritis." (PMID 40388679, 2025). "Filgotinib, a Janus kinase-1 preferential inhibitor, is one of the targeted synthetic DMARDs and has been evaluated for its efficacy and safety in the treatment of rheumatoid arthritis." (PMID 40388679, 2025). "Upadacitinib, taken at 15 mg once daily, is a JAK1 inhibitor approved to treat rheumatoid arthritis, psoriatic arthritis, atopic dermatitis and moderate-to-severe active ulcerative colitis." (PMID 41438753, 2025). "For example, tofacitinib, baricitinib, and upadacitinib, selective oral inhibitors of JAK1/3 or JAK1/2, are approved for the treatment of rheumatoid arthritis and other inflammatory diseases." (PMID 40650173, 2025). "Background/Objectives: Tofacitinib is a Janus kinase 1 and 3 inhibitor that was developed to treat rheumatoid arthritis." (PMID 40733122, 2025). "Filgotinib, which has been approved for use in rheumatoid arthritis (RA) and ulcerative colitis, is a JAK1 preferential inhibitor that suppresses downstream signals of IL-6, and it was anticipated that filgotinib would also be effective in iMCD." (PMID 39958406, 2025).
rheumatoid arthritis (continued). "Upadacitinib is an oral Janus kinase 1 (JAK1) selective inhibitor approved for the treatment of rheumatoid arthritis (RA) and other immune-mediated inflammatory diseases." (PMID 41404585, 2025). "The oral JAK1/2 inhibitor Baricitinib which has been clinically approved for the treatment of rheumatoid arthritis, has been demonstrated to induce M2 polarization significantly by directly inhibiting JAK1/STAT3 phosphorylation." (PMID 41562074, 2025). "Filgotinib is a selective inhibitor of JAK1 isoform and the latest of this class to receive official approval for use in rheumatoid arthritis." (PMID 38756936, 2024). "Upadacitinib is selective for JAK1 and is approved for the treatment of rheumatoid arthritis, psoriatic arthropathy, axial spondyloarthritis, atopic dermatitis, ulcerative dermatitis and Crohn's disease." (PMID 38665231, 2024). "Baricitinib is a JAK1/JAK2 inhibitor approved for rheumatoid arthritis, atopic dermatitis, alopecia areata, and juvenile idiopathic arthritis." (PMID 38731900, 2024). "Baricitinib, an oral selective inhibitor of Janus kinase 1 and 2, is approved for moderate and severe rheumatoid arthritis (RA) with insufficient response to conventional synthetic disease-modifying antirheumatic drugs." (PMID 39560543, 2024). "Baricitinib is a JAK1/JAK2 inhibitor used to treat severe rheumatoid arthritis, alopecia areata, and AD." (PMID 39076971, 2024). "Upadacitinib is an oral JAK-1 (JAK1) inhibitor that has been approved for the treatment of multiple immune-mediated inflammatory diseases including rheumatoid arthritis, psoriatic arthritis, and atopic dermatitis." (PMID 39258029, 2024). "Upadacitinib, an oral Janus kinase-1 (JAK-1)-selective inhibitor, is used to treat moderate to severe forms of rheumatoid arthritis, active psoriatic arthritis, ankylosing spondylitis, and severe atopic dermatitis." (PMID 37631077, 2023). "Baricitinib, a Janus kinase 1/2 inhibitor approved by the FDA for the treatment of rheumatoid arthritis, was recently found to inhibit both AAK1 and GAK and used as a potential inhibitor for 2019-novel CoV acute respiratory disease." (PMID 37196766, 2023). "There are also reports of IL-6-gp130–mediated signaling activity in rheumatoid arthritis, leading to JAK1 and STAT3 activity." (PMID 38139151, 2023). "Baricitinib is a JAK1/2 inhibitor that was approved for the treatment of adults with moderate-to-severe rheumatoid arthritis (RA)." (PMID 37194022, 2023). "Baricitinib is a selective JAK1/2 inhibitor approved for the treatment of rheumatoid arthritis and atopic dermatitis." (PMID 36902341, 2023). "Baricitinib is a JAK1/2 inhibitor with strong anti-inflammatory activity and is clinically used in the treatment of active rheumatoid arthritis." (PMID 36903446, 2023). "Tofacitinib is used against rheumatoid arthritis and other inflammatory diseases and mainly targets JAK1 and JAK3, with a lesser effect on JAK2." (PMID 36979068, 2023). "A clinical study comparing the periodontal status of patients with periodontitis and rheumatoid arthritis at baseline and 24 weeks after oral treatment with a JAK1-3 inhibitor indicated a reduction in periodontal inflammation." (PMID 37373437, 2023). "A recent study has assessed the safety and efficacy of a selective inhibitor of JAK1 SHR0302426 in rheumatoid arthritis patients, and this molecule has now entered a Phase 3 clinical trial (NCT04333771)." (PMID 36797236, 2023). "Of note, IL-32 contributes to activation of Janus-activated kinase-1 (JAK1) to promote immune-mediated inflammation of rheumatoid arthritis." (PMID 35545774, 2022). "Upadacitinib is a JAK1 inhibitor that was approved to treat rheumatoid arthritis by the FDA in August 2019." (PMID 35631587, 2022). "Baricitinib is a Janus kinase (JAK) inhibitor used to treat refractory rheumatoid arthritis and blocks the subtypes JAK1 and JAK2." (PMID 35096866, 2022).
rheumatoid arthritis (continued). "Filgotinib was first investigated for the treatment of rheumatoid arthritis, where the clinical results proved that rheumatoid arthritis can be treated with a selective inhibitor of JAK1." (PMID 35631587, 2022). "As a result, inhibiting JAK1 is regarded as a significant therapeutic strategy for the successful treatment of rheumatoid arthritis." (PMID 35529449, 2022). "Recently, baricitinib, a selective JAK1/2 inhibitor used to treat rheumatoid arthritis, has been investigated for the treatment of T2D and its complications." (PMID 36499659, 2022). "Filgotinib is a JAK1 inhibitor that is indicated for the treatment of active moderate to severe rheumatoid arthritis alone or in combination with methotrexate." (PMID 35356004, 2022). "For instance, IL-32 leads to activated JAK1, which promotes immune-mediated inflammation of rheumatoid arthritis." (PMID 35545774, 2022). "Upadacitinib is a second-generation oral selective JAK-1 inhibitor that is already approved for the treatment of rheumatoid arthritis." (PMID 34532638, 2021). "Filgotinib is a selective JAK1 inhibitor that has recently been approved in Europe for the treatment of rheumatoid arthritis (September 2020); it has also been evaluated in patients with CD in the FITZROY phase II trial." (PMID 33912062, 2021). "Several JAK1/2 inhibitors are used to treat autoimmune diseases such as rheumatoid arthritis, psoriasis, psoriatic arthritis and ulcerative colitis." (PMID 34531850, 2021). "Upadacitinib (RINVOQTM, Abbvie, IL, USA) is a JAK1-selective inhibitor, recently approved for the treatment of rheumatoid arthritis, with a four-hour half-life." (PMID 34209234, 2021). "Baricitinib is a small-molecule Janus kinase 1 (JAK1) e 2 (JAK2)” inhibitor that is currently approved for treatment of rheumatoid arthritis." (PMID 34072708, 2021). "Baricitinib, a Janus kinase (JAK) JAK1/JAK2 inhibitor used to treat rheumatoid arthritis, has been proposed to prevent intracellular uptake of SARS-CoV-2 by targeting the angiotensin-converting enzyme 2 (ACE2) receptor, suppressing cytokine storm." (PMID 35106192, 2021). "Oral JAK1 selective inhibitors, upadacitinib and filgotinib, were both reported to exert positive effect on active rheumatoid arthritis patients." (PMID 34384362, 2021). "The majority of our patients commenced JAK1/2 inhibition with baricitinib due to the earlier licensing of this medication for the treatment of rheumatoid arthritis but several patients commenced JAK1/3 inhibition with tofacitinib." (PMID 33721094, 2021). "Upadacitinib, a selective JAK1 inhibitor, has already been approved for the treatment of refractory rheumatoid arthritis and is currently under evaluation as induction and maintenance therapy for moderate to severe CD and UC." (PMID 33912062, 2021). "We recently reported that A77 1726, the active metabolite of the anti-rheumatoid arthritis drug leflunomide, is able to inhibit the replication of influenza A virus and porcine epidemic diarrhea virus by targeting JAK1 and JAK2." (PMID 33050000, 2020). "Tofacitinib and baricitinib are the pan-JAK inhibitors (JAK1/JAK3) approved for the treatment of moderate to severe rheumatoid arthritis but they showed dose-related toxicities." (PMID 35300367, 2020). "In this study, we demonstrated for the first time that the chronic administration of baricitinib, an oral JAK1/2 inhibitor approved for the treatment of rheumatoid arthritis, protects against the deleterious effects of chronic high-fat high-sugar feeding." (PMID 32413585, 2020). "In this study, we investigated the effects of the JAK1/2 inhibitor baricitinib, recently approved for the treatment of rheumatoid arthritis, in a murine high-fat-high sugar diet model." (PMID 32413585, 2020). "The JAK1/2 inhibitor baricitinib was approved in February 2017 for the treatment of moderate to severe active rheumatoid arthritis." (PMID 32413585, 2020).